ETS1 (ETS proto-oncogene 1, transcription factor)
Diseases named in the same sentence as ETS1 in open-access papers (continued):
Sharing a sentence is not in itself a finding about the gene and the disease.
colitis (1 paper, 2025). Inflammation of the colon. "Furthermore, mice deficient in Ets1‐SE exhibit resistance to colitis induced by Th1 cells." (PMID 40887825, 2025).
crescentic glomerulonephritis (1 paper, 2021). A histopathologic term for a pattern of diseases characterized by extensive crescent formation in the glomeruli; patients present clinically with rapid deterioration of renal function, and possible progression to end-stage renal failure within weeks or months. "The expression of ets1 has been reported to increase in both glomeruli and interstitium during the progression of rat crescentic glomerulonephritis." (PMID 34238215, 2021).
Crohn disease (1 paper, 2020). A gastrointestinal disorder characterized by chronic inflammation involving all layers of the intestinal wall, noncaseating granulomas affecting the intestinal wall and regional lymph nodes, and transmural fibrosis. "Through network analysis, we can introduce IL-7, GATA3, TXN, ETS-1, CCR7, CD28, and CD5 as Crohn’s disease-related critical genes and possible biomarker panel." (PMID 33585004, 2020). "Among the 81 queried DEGs related to Crohn’s disease, 7 genes (IL-7, GATA3, CD28, CD5, TXN, ETS-1, and CCR7) were introduced as dysregulated genes." (PMID 33585004, 2020).
cutaneous squamous cell carcinoma (1 paper, 2013). "The transcription factor Ets1 is expressed at low levels in epidermal keratinocytes under physiological conditions, but is over-expressed in cutaneous squamous cell carcinoma (SCC)." (PMID 24337118, 2013).
diabetic retinopathy (1 paper, 2017). "In this study, we found that CpG methylation regulates pathways that are used as pharmacological targets in diabetic retinopathy progression, such as angiogenesis (ETS1, HES5, PRDM16)." (PMID 28924151, 2017).
endometrial adenocarcinoma (1 paper, 2017). "BCL2 gene is known to be regulated by ETS152, and an over expression of ETS1 in human endometrial adenocarcinoma HEC-1-A cells can result in an increase in BCL2 protein expression." (PMID 28765546, 2017).
esophageal squamous cell carcinoma (1 paper, 2019). Esophageal squamous cell carcinoma (ESCC) is a type of esophageal carcinoma (EC) that can affect any part of the esophagus, but is usually located in the upper or middle third. "Our findings are also supported by results from studies on CD90(+) tumor initiating cell population from esophageal squamous cell carcinoma, where the deregulation of an ETS1/MMP signaling pathway and EMT figure prominently." (PMID 31306413, 2019).
Fibroadenoma (1 paper, 2004). A benign tumor of the breast characterized by the presence of stromal and epithelial elements. "In contrast to findings at the mRNA level, concentrations of the two main protein forms of Ets-1, that is, p51 and p52, were significantly increased in carcinomas compared to the fibroadenomas." (PMID 15365563, 2004).
fungal infection (1 paper, 2026). "To determine their contributions to fungal infection of insect hosts, we generated single and double deletion mutants of ETS1 and ETS6 in M. robertsii." (PMID 41114474, 2026). "Our reverse transcription‐quantitative PCR (RT‐qPCR) analysis indicated that both ETS1 and ETS6 were transcribed by M. robertsii during fungal infection and artificial growth." (PMID 41114474, 2026). "We examined the expression of several AMP genes and found significant downregulation of the antifungal genes Drs, Mtk, BaraA, Bomanin, and Daisho in both ETS1‐ and ETS6‐transgenic flies following fungal infection." (PMID 41114474, 2026).
glomerulonephritis (1 paper, 2018). A renal disorder characterized by damage in the glomeruli. "In the anti-Thy model of glomerulonephritis, the expression of ETS-1 is increased in the glomerular mesangium and to a lesser degree in podocytes and glomerular endothelium." (PMID 29970819, 2018). "In rats with anti-glomerular basement induced glomerulonephritis, there is also increased expression of ETS-1 in the glomeruli and in the interstitium." (PMID 29970819, 2018).
glomerulosclerosis (1 paper, 2021). A hardening of the kidney glomerulus caused by scarring of the blood vessels. "ets1 upregulation was reported to participate in glomerulosclerosis and renal interstitial fibrosis in experimental DN." (PMID 34238215, 2021).
gynecologic cancers (1 paper, 2020). "So, ETS1 might be a novel tumor suppressor for BRCA, or more generally for gynecologic cancers, that is well worth for future experimental and clinical research." (PMID 32412047, 2020).
Hashimoto thyroiditis (1 paper, 2025). An autoimmune disorder caused by the production of autoantibodies against thyroid tissue. "Normal (healthy) thyroid tissue had no to low ETS1 expression, while ETS1 could be detected at variable levels in Hashimoto’s thyroiditis, nodular goiter, and thyroid adenomas." (PMID 39941022, 2025).
hepatoblastoma (1 paper, 2019). Hepatoblastoma (HB) is a malignant hepatic tumor and is the most common pediatric liver cancer. "Although some studies have suggested that miR‐125b‐5p is associated with Ets1 in hepatoblastoma, as far as it is known, its target protein in HCC has not been reported." (PMID 31065520, 2019).
HIV-1 infection (1 paper, 2025). The type species of lentivirus and the etiologic agent of acquired immunodeficiency syndrome (AIDS). "Notably, ETS1 depletion also upregulated genes involved in the Wnt signaling pathway, HIV-1 viral life cycle, and HIV-1 infection pathways." (PMID 40198713, 2025). "The interplay between MALAT1 and ETS1 has not been previously reported for HIV-1 infection, and we propose that this represents a novel indirect mechanism of HIV-1 regulation by ETS1." (PMID 40198713, 2025).
Hyperinsulinemia (1 paper, 2022). An increased concentration of insulin in the blood. "Among them, Sin3a, Myc and Ets1 were upregulated by in vitro hyperinsulinemia." (PMID 34921686, 2022).
Hyperkeratosis (1 paper, 2009). Hyperkeratosis is a histopathological term defining a thickened stratum corneum and may be present in many different skin conditions, with many possible overlaps. "Like these strains, Ets1 BT mice develop extensive skin hyperplasia, abnormal terminal differentiation and hyperkeratosis." (PMID 19142229, 2009).
idiopathic inflammatory myopathies (1 paper, 2017). "In this study, we determined whether ETS1 gene polymorphisms confer susceptibility to idiopathic inflammatory myopathies (IIMs) in a northern Chinese Han population." (PMID 29030598, 2017).
Insulin resistance (1 paper, 2024). Increased resistance towards insulin, that is, diminished effectiveness of insulin in reducing blood glucose levels. "Conversely, the Ets1 adipocyte knock-out mice showed an enhanced energy expenditure, gained less weight, and were resistant to HFD induced insulin resistance." (PMID 38388532, 2024).
intracranial aneurysm (1 paper, 2023). "Interestingly, ETS1 has previously been implicated in human intracranial aneurysm (IA) formation, suggestively by mediating monocyte chemoattractant protein 1 expression in vascular smooth muscle cells to promote inflammation." (PMID 37698712, 2023).
intrahepatic cholangiocarcinoma (1 paper, 2022). A carcinoma that arises from the intrahepatic bile duct epithelium in any site of the intrahepatic biliary tree. "TPI1, also named ETS proto-oncogene 1 (ETS1), works as a downstream transcription factor of HIF-1a, which increases in a hypoxic environment and is highly correlated with recurrence rate of intrahepatic cholangiocarcinoma patients." (PMID 35406597, 2022).
ischemia (1 paper, 2018). A hypoperfusion of the BLOOD through an organ or tissue caused by a PATHOLOGIC CONSTRICTION or obstruction of its BLOOD VESSELS, or an absence of BLOOD CIRCULATION. "A transcription factor activity array showed that ETS-1 activity was increased 2-fold, 3 hours following ischemia and this activity was attenuated by NRG1." (PMID 29856744, 2018).
laryngeal carcinoma (1 paper, 2016). Carcinoma that arises from the laryngeal epithelium. "Analysis of ETS-1 levels in both the laryngeal carcinoma and adjacent normal tissues revealed that it was negatively correlated with miR-144-3p levels (p < 0.05)." (PMID 26826553, 2016).
lung tumor (1 paper, 2018). "Furthermore, expression levels of the downstream markers of the corresponding microRNAs, namely PTEN, MARCKs, TPM-1, PDCD4, SPRY-2, ETS-1, ZEB-2, FGFRL-1, EFNA-3, and k-RAS were downregulated in the lung tumor lesions of patients with the underlying condition compared to non-COPD patients." (PMID 29371906, 2018).
lymphoid neoplasm (1 paper, 2024). A neoplasm composed of a lymphocytic cell population which is usually malignant (clonal) by molecular genetic and/or immunophenotypic analysis. "Previous studies have demonstrated that aberrant modulation of EBF1, ETS1, ERG, and RUNX transcription factors has significant effects on lymphoid neoplasms derived from B cell progenitors." (PMID 38926853, 2024).
meningioma (1 paper, 2025). A generally slow growing tumor attached to the dura mater. "Targeting ETS1 became a potential direction for the treatment of meningioma." (PMID 40496867, 2025). "In conclusion, ETS1 could promote angiogenesis, and the poor prognosis of meningioma was mainly due to abundant blood vessels." (PMID 40496867, 2025). "Then we speculated that ETS1 knockout could inhibit the progression of meningioma." (PMID 40496867, 2025).
metastasis (1 paper, 2022). The spread or migration of cancer cells from one part of the body (where they first appeared) to another. "Fisher’s exact test of ETS1 expression and clinicopathological characteristics revealed that ETS1 expression was associated with tumor size and distant metastasis status but not with lymph node metastasis status and histological differentiation." (PMID 36477408, 2022).
muscular dystrophies (1 paper, 2022). "Three of these genes, ETS1, NR3C1 and JARID2, are common in all five muscular dystrophies with no previous association with any of the five muscular dystrophies based on bibliography." (PMID 35388741, 2022).
myeloid leukemia (1 paper, 2019). A clonal proliferation of myeloid cells and their precursors in the bone marrow, peripheral blood, and spleen. "Molecular investigations of myeloid leukemia cell lines revealed the presence of binding sites for ubiquitous (NF-1 and SP-1) and myeloid enriched (MZF-1-like protein, GATA-1, and Ets-1) transcription factors in the promoter region of the gene." (PMID 31709175, 2019).
myeloid neoplasm (1 paper, 2026). Proliferation of myeloid cells originating from a primitive stem cell. "Our findings expand the spectrum of dmin-associated oncogenic amplifications in myeloid neoplasms and highlight FLI1 and ETS1 as recurrent targets of 11q24-derived ecDNA amplification." (PMID 41982344, 2026).
myopia (1 paper, 2025). "We did not require prior myopia association at selection; consequently, while a small subset of variants had been examined in myopia (e.g., TGFβ1 rs1800469), the majority were exploratory inflammation-pathway candidates (e.g., ETS-1)." (PMID 41138034, 2025).
ocular cancer (1 paper, 2008). A benign or malignant neoplasm affecting the structures of the eye. "We therefore assessed whether this overproduction of ETS-1 was correlated with an upregulation of some of its known target genes in our model of ocular cancer." (PMID 18958307, 2008). "We previously showed that the transcription factors, ETS-1 and ETS-2, were both upregulated from P20 to three months in our ocular cancer model." (PMID 18958307, 2008). "This is consistent with previous studies that demonstrated the fact both ETS-1 and ETS-2 may play important roles in the development of ocular cancer." (PMID 18958307, 2008).
ocular tumor (1 paper, 2008). "The exposure time allowing the readily detection of ETS-1 and ETS-2 by western blotting in the retina of wild-type CB6 mice gave highly saturated signals for ETS-1 protein extracted from eyes affected by ocular tumor." (PMID 18958307, 2008). "Our findings suggest that the genes encoding ETS-1 and/or ETS-2 may play a role in the emergence and/or progression of ocular tumor." (PMID 18958307, 2008). "Our data suggest that ETS-1 and ETS-2 are involved in one or more signaling pathways activating the expression of a set of genes involved in ocular tumor progression and the probable acquisition of high metastatic potential by this tumor." (PMID 18958307, 2008). "We then investigated ETS-1 and ETS-2 gene expressions in a mouse model of pigmented ocular neoplasm." (PMID 18958307, 2008). "Interestingly, in triplicate experiments using semi-quantitative PCR and western blotting to compare ocular tumors in Tyrp-1 mice with WT eyes at the same age, we found that ETS-2 mRNA levels were higher than ETS-1 mRNA levels, but ETS-1 protein levels were higher than ETS-2 protein levels." (PMID 18958307, 2008). "The role of two members of the ETS (E26 avian leukemia oncogene) family of transcription factors, ETS-1 and ETS-2, has been investigated in many cancers but has not yet been studied in ocular tumors." (PMID 18958307, 2008). "However, the results obtained did not determine whether ETS-1 or ETS-2 was increased exclusively in the retina and/or RPE per se and in the ocular tumor only or throughout the whole eye." (PMID 18958307, 2008).
Oral ulcer (1 paper, 2011). Erosion of the mucous mebrane of the mouth with local excavation of the surface, resulting from the sloughing of inflammatory necrotic tissue. "TNFAIP3 and ETS1 were significantly associated with most subphenotypes, but none of them showed association with oral ulcers." (PMID 22087647, 2011). "Interestingly, SNPs rs6590330 and rs4937333 (ETS1) showed significance in the patient groups without the subphenotypes of oral ulcers and neurologic disorder when compared with the patient groups with these subphenotypes." (PMID 22087647, 2011).
osteoporosis (1 paper, 2021). A condition of reduced bone mass, with decreased cortical thickness and a decrease in the number and size of the trabeculae of cancellous bone (but normal chemical composition), resulting in increased fracture incidence. "ETS proto-oncogene 1 (ETS1) has been implicated in osteoporosis (OP), but the exact molecular mechanisms are complex." (PMID 33746773, 2021).
pancreatic adenocarcinoma (1 paper, 2015). "To further evaluate the role of ETS-1 during EMT, we inhibited ETS-1 expression with an ETS-1-specific shRNA and assessed its effects on the expression of N-cadherin, E-cadherin and VEGF in the Panc-1 cell line, a highly metastatic epithelial-pancreatic adenocarcinoma cell line." (PMID 25421630, 2015).
polycystic ovary syndrome (1 paper, 2024). A disorder that manifests as multiple cysts on the ovaries. "Ets1 has been implicated in the pathogenesis of polycystic ovary syndrome, while Irx3 has been reported to be essential for oocyte quality control through ECM production." (PMID 39441825, 2024).
posterior uveitis (1 paper, 2024). Inflammation of the choroid as well as the retina and vitreous body. "Our findings suggest ETS-1 blockade would promote rather than inhibit retinal transendothelial migration of leukocytes, and thus imply that ETS-1 is unlikely to be a viable drug target for non-infectious posterior uveitis." (PMID 38984117, 2024). "Thus ETS-1-targeting would be expected to promote rather than inhibit retinal transendothelial migration of leukocytes in non-infectious posterior uveitis." (PMID 38984117, 2024). "Based on published literature implicating transcription factor ETS-1 as an activator of ICAM1 gene transcription, we considered it a promising drug target for blocking the induction of ICAM-1 during non-infectious posterior uveitis." (PMID 38984117, 2024).
prostate tumours (1 paper, 2021). "ETS1‐overexpressing prostate tumours are associated with increased cell migration, invasion and induction of epithelial‐to‐mesenchymal transition." (PMID 33509203, 2021).
pulpitis (1 paper, 2021). Inflammation of the dental pulp. "Six transcription factors (i.e., GATA2, ETS1, FOXP3, STAT1, FOS, and JUN) were identified to play pivotal roles in pulpitis." (PMID 33777260, 2021). "Several transcription factors have been identified to be involved in the TF-gene regulatory network of pulpitis, including GATA2, ETS1, FOXP3, STAT1, FOS, and JUN." (PMID 33777260, 2021).
RASopathy (1 paper, 2017). Developmental syndromes caused by germline mutations (or in rare cases by somatic mosaicism) in genes that alter the Ras subfamily and mitogen-activated protein kinases that control signal transduction. "In addition, two other noteworthy loci (one between KIRREL3 and ETS1, the other between GATA3 and CELF2) overlap between top results from ASD epistasis and RASopathy modifier mapping and contain genes of particular interest." (PMID 28076348, 2017).
retinopathy of prematurity (1 paper, 2017). A bilateral retinopathy characterized by neovascularization, scarring, retinal detachment, and eventually blindness. "Levels of THBS1, MMP8, MMP9, MMP25, TIMP2 and TIMP3 increased as severity of BPD and retinopathy of prematurity (ROP) increased, whereas ETS1, LEF1 and SPOCK2 exhibited the opposite trend." (PMID 28103583, 2017).
sarcoidosis (1 paper, 2022). Sarcoidosis is a multisystemic disorder of unknown cause characterized by the formation of immune granulomas in involved organs. "In a prior gene co-expression analyses of peripheral blood and cutaneous lesions we noted that transcription factors, such as ETS1, IKZF3, LEF1, MYC, RORA, and SPI1 (PU.1), may be central players in aberrant processes associated with sarcoidosis." (PMID 36311769, 2022).
scleroderma (1 paper, 2006). Scleroderma is a rare autoimmune connective tissue disorder characterized by abnormal hardening of the skin and, sometimes, other organs. "Although Ets-1 DNA binding activity is increased in scleroderma fibroblasts, the Ets family member Fli-1 has reduced expression in this cell type; however, the consequences of altering the Ets-1/Fli-1 ratios on mesenchymal biology has yet to be fully appreciated." (PMID 16469114, 2006).
skin aging (1 paper, 2021). The gradual irreversible changes in structure of skin that occur as a result of the passage of time.. "TF ETS1, which was regulated through the signaling pathway activated by ligand NGF, has been identified to be associate with skin aging." (PMID 34073305, 2021).
skin infection (1 paper, 2023). An inflammatory process affecting the skin, caused by bacteria, viruses, parasites, or fungi. "This role of DETCs was only revealed in mice lacking IL17RA, but not in WT mice, which is consistent with the lack of observed susceptibility to S. aureus skin infection in Ets1 KO animals." (PMID 37691956, 2023).
skin melanomas (1 paper, 2021). "Many of them were previously appreciated in the genome of skin melanomas (e.g., MITF, NOTCH2, PD-L1 and JAK2 amplifications, or CDKN2A deletions); however, the CNAs in genomic locations harboring PAX5, ETS1, BCL7, RAD51, APAF1, FOXO3 and CTNNA1 are novel." (PMID 33779796, 2021).
skin pigmentation disorder (1 paper, 2025). A pigmentation disease that involves the zone of skin. "This analysis provides valuable insights into potential therapeutic targets for conditions involving MC dysfunction, while further research is needed to fully elucidate the molecular basis of Ets-1 deficiency in skin pigmentation disorders." (PMID 41310821, 2025).